UCKL1 (uridine-cytidine kinase 1 like 1)
Description:
Phosphorylates uridine and cytidine to uridine monophosphate and cytidine monophosphate.
Synonyms: URKL1; FLJ20517; UCK1L
Tractability: PROTAC: UniProt records ubiquitination sites on it; ubiquitination databases record sites on it; its protein half-life has been measured.
Gene: Protein-coding gene on chromosome 20 (63,939,828 to 63,956,480, reverse strand). Ensembl gene ENSG00000198276.
Subcellular location: Cytoplasm (Isoform 1); Nucleus; Cytoplasm (Isoform 3)
Subcellular location (Human Protein Atlas): Endoplasmic reticulum
Pathways (Reactome):
Metabolism: Pyrimidine salvage
Gene Ontology:
Molecular function: cytidine kinase activity; protein binding; uridine kinase activity; ATP binding; kinase activity
Biological process: pyrimidine nucleoside salvage; carbohydrate derivative biosynthetic process; CMP biosynthetic process; CTP salvage; nucleobase-containing small molecule metabolic process; pyrimidine-containing compound salvage; UMP salvage
Cellular component: cytoplasm; nucleus; cytosol
Genetic constraint (gnomAD): Loss-of-function variants: 65 observed, 56.88 expected, observed/expected ratio (o/e) 1.14, 90% interval 0.94 to 1.4. The synonymous counts are far from expectation, so gnomAD's model fits this gene poorly and the ratio says little. Missense variants: 703 observed, 750.63 expected, observed/expected ratio (o/e) 0.94, 90% interval 0.88 to 1. Synonymous variants: 410 observed, 312.82 expected, observed/expected ratio (o/e) 1.31, 90% interval 1.21 to 1.42.
Homologues: Orthologues: chimpanzee UCKL1 (99% identical), guinea pig UCKL1 (95% identical), mouse Uckl1 (95% identical), rat Uckl1 (94% identical), pig UCKL1 (92% identical), dog UCKL1 (91% identical), macaque UCKL1 (89% identical), tropical clawed frog UCKL1 (80% identical), zebrafish uckl1b (79% identical), zebrafish uckl1a (72% identical), Drosophila melanogaster l(2)k01209 (59% identical). Paralogues in human: UCK2 (23% identical), UCK1 (22% identical), UPRT (19% identical).
Diseases named in the same sentence as UCKL1 in open-access papers:
UCKL1 is named in the same sentence as 18 diseases in open-access papers, as found by Europe PMC text mining. Sharing a sentence is not in itself a finding about the gene and the disease. The quoted sentences say what the papers report.
breast carcinoma (4 papers, 2013 to 2025). "S Many reports have revealed the oncogenic effects of UCKL1 in hepatocellular carcinoma, breast cancer, and colorectal cancer." (PMID 40860343, 2025). "Serum UCKL-1 mRNA levels were found to be increased 100–1000 times in patients with breast cancer, with the highest UCKL-1 expression in Luminal A and HER2 (ERRB2) subtypes." (PMID 38427106, 2024). "UCKL1 is a uridine-cytidine kinase that plays a role in cell proliferation and survival and is highly expressed in breast cancer." (PMID 36685859, 2022).
hepatocellular carcinoma (3 papers, 2017 to 2025). A malignant tumor that arises from hepatocytes. "Studies have found that upregulation of UCKL1 expression may be an indicator of adverse prognosis in hepatocellular carcinomas." (PMID 38427106, 2024).
colorectal cancer (2 papers, 2025). A primary or metastatic malignant neoplasm that affects the colon or rectum. "Within these pleiotropic genes, MXR5 was associated with colorectal cancer; TRPM1 and UCKL1 were linked to prostate cancer, and TTN was associated with both cancer types." (PMID 41234971, 2025).
lung carcinoma (2 papers, 2020 to 2024). "We showed that 6% lung cancer patients were with UCK2 amplification and 5% lung cancer patients were with UCKL1 amplification." (PMID 32638267, 2020).
prostate carcinoma (2 papers, 2016 to 2025). A carcinoma that arises from epithelial cells of the prostate gland. "This is consistent with both genomic and proteomic data demonstrating highest levels of UCKL-1 in the most aggressive, metastatic breast and prostate cancer cells." (PMID 32083188, 2016).
human papillomavirus infection (1 paper, 2024). "KEGG pathway visualization showed that UCKL1 and GSTT1 were upregulated in the drug metabolism pathway, and HLA-G and MAML2 were significantly upregulated in the human papillomavirus infection pathway." (PMID 38427106, 2024).
leukemia (1 paper, 2024). A malignant (clonal) hematologic disorder, involving hematopoietic stem cells and characterized by the presence of primitive or atypical myeloid or lymphoid cells in the bone marrow and the blood. "Down-regulating the expression of UCKL-1 in leukemia cells by RNA interference was found to aggravate apoptosis and slow down the cell cycle process, thus reducing the growth rate of leukemia cells with small interference with UCKL-1 RNA processing." (PMID 38427106, 2024).
liver cirrhosis (1 paper, 2018). "Since UCKL-1 was implicated in enhanced cell proliferation, as was mentioned earlier, and it could be involved in carcinogenesis, we expected a remarkable difference in its expression in cases of HCC compared with HCC-free liver cirrhosis patients." (PMID 30344298, 2018).
lung adenocarcinoma (1 paper, 2024). A carcinoma that arises from the lung and is characterized by the presence of malignant glandular epithelial cells. "There were 5 genes with a causal relationship to lung adenocarcinoma, including RNASET2, MPZL2, MPZL3, CHRNA5 and UCKL1." (PMID 38834983, 2024).
lymphoma (1 paper, 2016). A malignant (clonal) proliferation of B- lymphocytes or T- lymphocytes which involves the lymph nodes, bone marrow and/or extranodal sites. "The lymphoma line RMA-S is a prototypic NK tumor target and therefore a good model for evaluating the effect of UCKL-1 over-expression on tumor susceptibility to NK killing." (PMID 32083188, 2016).
myocardial infarction (1 paper, 2025). Gross necrosis of the myocardium, as a result of interruption of the blood supply to the area, as in coronary thrombosis. "In a murine model of myocardial infarction (MI), individual knockdown of either UCK2 or UCKL1 significantly ameliorated pathological remodeling, evidenced by preserved cardiac function, attenuated hypertrophy, and reduced pulmonary edema." (PMID 41457201, 2025).
tumor (9 papers, 2016 to 2025). "Uridine-cytidine kinase-like-1 (UCKL-1) increases tumor cell survival, while NKLAM ubiquitinates UCKL-1, causing its degradation." (PMID 39223632, 2024). "Over-expression of UCKL-1 increases the expression of cyclin D and cyclin E, which are associated with both cell cycle progression and tumor resistance to apoptosis." (PMID 32083188, 2016). "Our previous studies demonstrated that down-regulation of UCKL-1 in K562 human tumor cells by RNA interference causes a decrease in proliferation, an increase in spontaneous apoptosis and in the susceptibility to lysis by NK cells." (PMID 32083188, 2016). "Since uridine kinase expression is associated with cancer growth, we hypothesized that upon NK-tumor cell interaction, during the process of granule exocytosis, NKLAM may be able to interact with tumor-associated proteins, like UCKL-1." (PMID 33192571, 2020). "This would result in loss of UCKL-1 expression in the tumor cell, thereby impacting its survival." (PMID 33192571, 2020). "Tumor cells that express less UCKL-1 undergo apoptosis as a result, rendering them more sensitive to NK cell cytotoxicity." (PMID 39223632, 2024). "UCKL1 is a catalytically active protein with uridine cytidine kinase and phosphoribosyltransferase, which can promote the growth of tumor cells." (PMID 38427106, 2024). "In these pathways, some genes including an oxidative stress response gene (GSTO1), a metastasis suppressor gene (NME6), and a gene involved in tumor cell survival (UCKL1), were upregulated." (PMID 37744913, 2023). "To model the potential effect of NKLAM on reduction of UCKL-1 expression in tumor cells, we performed siRNA experiments." (PMID 33192571, 2020). "Conversely, over-expression of UCKL-1 protects tumor cells from NK killing and enhances tumor survival in vitro and in vivo." (PMID 33192571, 2020). "Downregulation of UCKL-1 in tumor cells by siRNA slows their proliferation, induces apoptosis and enhances their susceptibility to NK-mediated lysis." (PMID 33192571, 2020). "Tumor burden was greatest in NKLAM KO mice injected with UCKL-1 transfected RMA-S cells than in any other group." (PMID 32083188, 2016). "We show that UCKL-1 over-expression protects tumor cells from NK-mediated and drug-induced apoptosis, enhances tumor survival in vitro and in vivo and increases the rate of tumor cell proliferation." (PMID 32083188, 2016). "The involvement of UCKL-1 in proliferation, apoptosis, and susceptibility to NK-mediated cytolysis led us to examine NF-κB activity in tumor cells with varying levels of UCKL-1." (PMID 32083188, 2016). "Here we show that UCKL-1 over-expression protects tumor cells from NK killing and enhances tumor survival in vivo." (PMID 32083188, 2016). "Tumor burden was greatest in NKLAM KO mice injected with UCKL-1 transfected tumor cells than in any other group, indicating that UCKL-1 over-expression protects tumor cells from immune-mediated destruction in vivo." (PMID 32083188, 2016). "Sequence analysis indicates that UCKL-1 has homology to uridine kinases, enzymes that play a role in DNA and RNA synthesis and that are often up-regulated in tumor cells." (PMID 32083188, 2016). "Based upon our observations and those of others, the present study was initiated to further elucidate the role of UCKL-1 in tumor survival in vitro and in vivo." (PMID 32083188, 2016). "Enhanced expression of NKLAM, with concomitant reduction in UCKL-1 within the tumor cell, results in more tumor cell lysis." (PMID 32083188, 2016). "More than twice as many UCKL-1 transfected tumor cells than control-transfected cells survived in the lungs of WT mice." (PMID 32083188, 2016). "Current studies are focused on further investigating the function of UCKL-1 in tumor growth and metastasis and determining the mechanism by which UCKL-1 influences NF-κB activity." (PMID 32083188, 2016).
tumor (continued). "Overall, these studies demonstrate that tumor cells that over-express UCKL-1 are more resistant to NK-mediated cytotoxicity in vitro and in vivo." (PMID 32083188, 2016). "NF-κB activity is higher in tumor cells transfected with UCKL-1 than in control transfected cells, suggesting at least one possible mechanism by which UCKL-1 influences tumor growth and survival." (PMID 32083188, 2016). "UCKL-1 interacts with natural killer lytic-associated molecule (NKLAM), a protein associated with natural killer (NK) cell-mediated anti-tumor activity." (PMID 32083188, 2016). "Uridine cytidine kinase like-1 (UCKL-1) is a largely uncharacterized protein over-expressed in many tumor cells, especially in highly malignant, aggressive tumors." (PMID 32083188, 2016). "UCKL-1 also has a much broader role, protecting tumor cells from spontaneous and drug-induced apoptosis and increasing tumor cell proliferation." (PMID 32083188, 2016). "Microarray analyses indicate that UCKL-1 levels are higher in many tumor cells compared to normal cells." (PMID 32083188, 2016). "This suggests that UCKL-1 plays an important role in tumor cell survival." (PMID 30344298, 2018). "A multivariate analysisof prognostic factors for HCC recurrence showed that the best predictivefactors for these conditions were UCKL-1 expression in tumor, vascularinvasion, and HCC treatment modality, other than liver transplantation (oddsratios: 1.029, 18.143 and 11.984, R2 = 0.633,p = 0.002)." (PMID 29104783, 2017). "The fact that UCKL-1 is a substrate for NKLAM suggests that UCKL-1 may provide resistance to NK killing in tumor cells." (PMID 32083188, 2016). "We evaluated whether UCKL-1 over-expression would protect tumor cells from NK-mediated killing through induction of apoptosis." (PMID 32083188, 2016). "The increased nuclear translocation and activity of NF-κB in cells over-expressing UCKL-1 may enhance tumor progression." (PMID 32083188, 2016). "Tumor cell lines K562 and RMA-S and the mouse fibroblast cell line 3T3 were transfected with an empty plasmid vector (pControl) or plasmid encoding Flag-tagged UCKL-1 (pFlag-UCKL-1)." (PMID 32083188, 2016). "By altering NF-κB activity, UCKL-1 expression may affect many elements of tumor progression." (PMID 32083188, 2016). "In order to monitor the expression levels of the UCKL1 protein in HCC, immunohistochemistry on tumor samples was performed." (PMID 30344298, 2018). "Nuclear factor-kappa B (NF-κB) activity is higher in tumor cells transfected with UCKL-1 compared to control transfected cells, suggesting at least one possible mechanism by which UCKL-1 influences tumor growth and survival." (PMID 32083188, 2016). "More UCKL-1 transfected RMA-S-GFP cells persisted in the lungs of WT and NKLAM KO mice than control-transfected RMA-S-GFP cells after intravenous administration of tumor cells." (PMID 32083188, 2016).
cancer (3 papers, 2016 to 2025). A tumor composed of atypical neoplastic, often pleomorphic cells that invade other tissues. "UCKL-1 is often upregulated in cancers and is proposed as a biomarker for several cancer types." (PMID 33192571, 2020). "The higher levels of UCKL-1 observed in cancer cells may be a mechanism to enhance their survival by increasing their resistance to immune-mediated killing." (PMID 32083188, 2016). "Once the method of action of UCKL-1 is determined, it may be possible to design new cancer therapeutics that target UCKL-1 directly, or indirectly by enhancing NK and NKLAM function." (PMID 32083188, 2016).
UCKL1 also shares sentences with these, for which no sentence is quoted: asthma (1 paper); Cirrhosis (1); heart failure (1); inverted papilloma (1); retinoblastoma (1).